DAAM1 (dishevelled associated activator of morphogenesis 1)
Description:
Binds to disheveled (Dvl) and Rho, and mediates Wnt-induced Dvl-Rho complex formation. May play a role as a scaffolding protein to recruit Rho-GDP and Rho-GEF, thereby enhancing Rho-GTP formation. Can direct nucleation and elongation of new actin filaments. Involved in building functional cilia. Involved in the organization of the subapical actin network in multiciliated epithelial cells (By similarity). Together with DAAM2, required for myocardial maturation and sarcomere assembly (By similarity). During cell division, may regulate RHOA activation that signals spindle orientation and chromosomal segregation.
Synonyms: KIAA0666
Tractability: Antibody: its Gene Ontology location is reachable by antibodies, with high confidence; the Human Protein Atlas places it where antibodies can reach. PROTAC: ubiquitination databases record sites on it; its protein half-life has been measured.
Gene: Protein-coding gene on chromosome 14 (59,188,646 to 59,371,405, forward strand). Ensembl gene ENSG00000100592.
Subcellular location: Cytoplasm; Cytoplasm, cytoskeleton, cilium basal body
Subcellular location (Human Protein Atlas): Cytosol; Plasma membrane
Pathways (Reactome):
Signal Transduction: CDC42 GTPase cycle; PCP/CE pathway; RHO GTPases Activate Formins; RHOA GTPase cycle; RHOB GTPase cycle; RHOC GTPase cycle
Gene Ontology:
Molecular function: identical protein binding; protein binding; actin binding; small GTPase binding
Biological process: Wnt signaling pathway, planar cell polarity pathway; actin cytoskeleton organization; presynaptic actin cytoskeleton organization
Cellular component: ciliary basal body; membrane; motile cilium; stress fiber; cytosol; perinuclear region of cytoplasm; cytoplasm; glutamatergic synapse; presynapse; synapse
Genetic constraint (gnomAD): Loss-of-function variants: 49 observed, 122.17 expected, observed/expected ratio (o/e) 0.4, 90% interval 0.32 to 0.51. The upper end of that interval is the gene's LOEUF score, 0.51, which puts it in group 2 of 6, group 1 being the genes least tolerant of losing a copy. Missense variants: 1,106 observed, 1,297.8 expected, observed/expected ratio (o/e) 0.85, 90% interval 0.81 to 0.9. Synonymous variants: 436 observed, 441.43 expected, observed/expected ratio (o/e) 0.99, 90% interval 0.91 to 1.07.
Homologues: Orthologues: chimpanzee DAAM1 (100% identical), macaque DAAM1 (99% identical), dog DAAM1 (99% identical), pig DAAM1 (98% identical), rabbit DAAM1 (98% identical), mouse Daam1 (97% identical), rat Daam1 (97% identical), guinea pig DAAM1 (97% identical), tropical clawed frog daam1 (86% identical), zebrafish daam1b (82% identical), zebrafish daam1a (81% identical), Drosophila melanogaster DAAM (51% identical), and 1 more. Paralogues in human: DAAM2 (69% identical), FMNL2 (25% identical), DIAPH1 (24% identical), FMNL1 (24% identical), FMNL3 (24% identical), DIAPH2 (22% identical), DIAPH3 (22% identical), INF2 (21% identical), FMN2 (18% identical), FHOD3 (18% identical), GRID2IP (18% identical), FHOD1 (16% identical), and 6 more.
Diseases named in the same sentence as DAAM1 in open-access papers:
DAAM1 is named in the same sentence as 47 diseases in open-access papers, as found by Europe PMC text mining. Sharing a sentence is not in itself a finding about the gene and the disease. The quoted sentences say what the papers report.
breast carcinoma (15 papers, 2012 to 2025). "Dishevelled-associated activator of morphogenesis 1 (DAAM1) is a critical driver in facilitating metastasis in breast cancer (BrCa)." (PMID 34453038, 2021). "Wnt5a promotes breast cancer cell migration via Dishevelled 2 (Dvl2)/Dishevelled-associated activator of morphogenesis 1 (Daam1)/RhoA signaling pathway." (PMID 28289332, 2017). "Immunohistochemical analysis of breast cancer tissue microarrays revealed frequent colocalization of polycystin‐1 and Daam1 in highly collagen‐rich areas, with a positive correlation (r = 0.417) between their expression levels." (PMID 40789101, 2025). "Our previous research revealed that DAAM1 was highly expressed in breast cancer tissues and was mediated by YWHAZ protein, and the cooperation between YWHAZ and DAAM1 contributed to breast cancer metastasis." (PMID 36311172, 2022). "Downregulation of Daam1 or the knockdown of Wnt5a inhibits migration and invasion of breast cancer cells." (PMID 34178477, 2021). "Some examples of strong correlations are DAAM1 in breast cancer; FMNL1 in nasopharyngeal cancer, non-small cell lung cancer, and clear cell renal cell cancer; and of FMNL3 in colorectal cancer." (PMID 34685534, 2021). "Examples of this function are DIAPH1-3 and DAAM1 in breast cancer, DIAPH1 in glioma, FMNL1 in nasopharyngeal carcinoma, FMNL2 in colorectal cancer, and FHOD1 in oral squamous carcinoma." (PMID 34685534, 2021). "Dishevelled-associated activator of morphogenesis 1 (DAAM1) is a member of microfilament-related formins and mediates cell motility in breast cancer (BrCa)." (PMID 30911286, 2019). "WNT-5A induces RhoA activation via DVL and Daam1 in breast cancer cells or via PI3K/AKT signaling in gastric cancer cells." (PMID 26514730, 2016). "In this study, we demonstrated that Wnt5a promotes MDA-MB-231 breast cancer cell migration by activating Dvl2/Daam1." (PMID 22655072, 2012). "Taken together, we demonstrated for the first time that Wnt5a promotes breast cancer cell migration via Dvl2/Daam1/RhoA." (PMID 22655072, 2012). "In summary, we presented the first direct evidence that Wnt5a promotes breast cancer cell migration via Dvl2/Daam1/RhoA." (PMID 22655072, 2012). "We showed here that Wnt5a activated Dvl2, Daam1 and RhoA, and promoted migration of breast cancer cells, which was, however, abolished by Secreted Frizzled-related protein 2 (sFRP2) pretreatment." (PMID 22655072, 2012). "DAAM1 was overexpressed in breast cancer and promoted cancer metastasis in response to Wnt5a." (PMID 35281277, 2022). "Overexpression of DAAM1 is thought to be related to breast cancer metastasis and bad prognosis." (PMID 32766227, 2020). "Our previous studies find that active DAAM1 is involved in Wnt5a/Dishevelled 2 and Collagen/Integrin αvβ3 signaling pathways, resulting in the elevation of the migratory and haptotatic ability of breast cancer (BrCa) cells." (PMID 30911286, 2019). "Constitutively active ΔDAD-Daam1 induced RhoA activation, the formation of stress fibers, and migration of MCF-7 cells, indicating that Daam1 may be specifically required for the activation of Dvl2 after Wnt5a treatment in breast cancer cells." (PMID 22655072, 2012). "In addition to breast cancer, DAAM1 also plays oncogenic roles in multiple tumors." (PMID 35281277, 2022). "Then, we examined whether Daam1 could activate RhoA in other human breast cancer cells." (PMID 22655072, 2012). "Consistent with the notion that DAAM1 inhibits and DAAM2 promotes ACM-induced BCC migration, decreased expression of DAAM1 in breast cancer patients resulted in a significant reduction in survival." (PMID 31142743, 2019).
lung carcinoma (6 papers, 2010 to 2023). "PTPN3 suppresses lung cancer cell proliferation and migration by counteracting Src-mediated disheveled-associated activator of morphogenesis 1 (DAAM1) activation and actin polymerization and by promoting EGFR endocytic degradation." (PMID 35957898, 2022). "The latest study found that tyrosine phosphorylation at the site of 652 in DAAM1 protein is critical to its molecular function, and the phosphorylation of DAAM1 mediated by the oncogene SRC enhances the invasiveness of lung cancer cells." (PMID 34453038, 2021). "Daam1 overexpression is closely related to lung cancer cell metastasis, especially SCLC." (PMID 37636026, 2023). "In addition, Src-mediated activation of DAAM1 induced actin polymerization and thus promoted lung cancer metastasis." (PMID 35281277, 2022). "Besides, the tyrosine phosphorylation of DAAM1 modulates its homodimer formation and actin polymerization, which is essential for lung cancer invasiveness." (PMID 34453038, 2021). "Daam1 may also play a role in the PCP pathway in lung cancer." (PMID 37636026, 2023). "Reversible tyrosine phosphorylation of DAAM1 by Src and PTPN3 regulated actin dynamics and lung cancer invasiveness." (PMID 32498343, 2020). "This colocalization with actin stress fibers by the anti-DAAM1 staining was confirmed by confocal imaging of DAAM1 positive COS-7 and U2OS lines and was absent from H460 lung cancer cells that lack DAAM1." (PMID 20927366, 2010).
melanoma (6 papers, 2020 to 2025). A malignant, usually aggressive tumor composed of atypical, neoplastic melanocytes. "This identified somatic eQTLs frequently mutated in melanoma, including 12 that were almost exclusively mutated in melanoma, and two loci that regulate the expression of DAAM1 (191 bp downstream) and HYI (95 kb away)." (PMID 36171609, 2022). "Previous studies report that DAAM1 mediates the migration of multiple cancer cells via Rho signaling pathways, including BrCa cells, glioblastoma cells, melanoma cells, ovarian cancer cells, esophageal squamous cell carcinoma cells, and osteosarcoma cells." (PMID 34453038, 2021). "The in vivo tumour-initiating capacity of DAAM1 in melanoma was further validated using an additional melanoma cell line A375M2." (PMID 33082334, 2020). "Furthermore, WNT11 stimulated RhoA activity and downstream Myosin II levels in melanoma cells, but this effect was lost when DAAM1 was silenced." (PMID 33082334, 2020). "Importantly, our work has unravelled a crucial role for DAAM1 in promoting both tumour and metastasis initiation and later metastatic outgrowth in melanoma by regulating amoeboid features." (PMID 33082334, 2020). "We also used the PRJEB23709, GSE176307, and IMvigor210 cohorts to check the prognostic value of DAAM1 in melanoma and urothelium cancer, and the results showed that DAAM1 could not predict prognosis in melanoma and urothelium cancer patients." (PMID 36311172, 2022).
ovarian carcinoma (5 papers, 2020 to 2025). A malignant neoplasm originating from the surface ovarian epithelium. "The finding that DAAM1 up-regulation was connected with cell migration and invasion in ovarian cancer has been displayed by a former research." (PMID 33088221, 2020). "Authors documented that inhibition of DAAM1 prevents Wnt/Fz activation of Rho signaling and summarized that miR-208-5p/DAAM1 axis may be a novel prognostic marker/clinical target in metastatic phenotype of ovarian cancer." (PMID 32443784, 2020).
diabetes (2 papers, 2013 to 2015). "The fact that the embryopathy induced by maternal diabetes appeared to display certain synergism with the genotype at the Daam1 locus suggested that the maternal diabetic state affects the non-canonical Wnt pathway, with the Daam1 mutation exaggerating the diabetes-induced eye abnormalities." (PMID 25540130, 2015). "Indeed, studying the effects of maternal diabetes on the Wnt-PCP pathway demonstrated that there was strong association with the Daam1 genotype, whereby the embryopathy observed in Daam1gt/+ mutant embryos of diabetic dams was more severe." (PMID 25540130, 2015). "In addition to the gene expression analysis and the interaction between the Daam1 mutation and diabetes in eye development, a number of morphological and apicobasal cell polarity defects were found in the optic vesicles of embryos that had been exposed to glucose." (PMID 25540130, 2015). "The eye defects observed in the Daam1 mutant (Daam1+/gt and Daam1gt/gt) embryos resembled those found in embryos that had been exposed to maternal diabetes, which prompted us to analyze the combination of these two factors in the context of eye development." (PMID 25540130, 2015). "The development of DORV in Daam1+/gt embryos from diabetic dams demonstrates the interaction between diabetes and the Wnt-PCP pathway, because this defect has been observed only in Daam1gt/gt embryos." (PMID 25540130, 2015). "Maternal hyperglycaemia is known to affect the expression of components of the Wnt-PCP pathways, including Wnt5a, Vangl2, Rock1 and Daam1 in mouse embryos, suggesting that abnormal Wnt-PCP signalling might underlie diabetic embryopathies." (PMID 25540130, 2015). "The Daam1+/+ and Daam1+/gt embryos that were exposed to diabetes and studied here developed different heart defects, although the most common one was the misalignment of the great arteries, leading to DORV (no such heart defects were evident in the control embryos)." (PMID 25540130, 2015).
esophageal squamous cell carcinoma (2 papers, 2021 to 2022). Esophageal squamous cell carcinoma (ESCC) is a type of esophageal carcinoma (EC) that can affect any part of the esophagus, but is usually located in the upper or middle third. "ROR1 strongly associates with ROR2, making up the receptor for Wnt5a signaling and activates RhoA through Daam1 in esophageal squamous cell carcinoma (ESCC) and glioblastoma." (PMID 35625853, 2022).
idiopathic pulmonary arterial hypertension (2 papers, 2017). A sporadic form of pulmonary arterial hypertension (PAH) characterized by elevated pulmonary arterial resistance leading to right heart failure. "DAAM1 is overexpressed in pulmonary arteries in idiopathic pulmonary arterial hypertension." (PMID 28521775, 2017).
neuroblastoma (2 papers, 2013 to 2017). Neuroblastoma (NB) is the most common solid, extracranial childhood tumor. "Recent studies have implicated Daam1, Daam2 and other formin-family genes in the migration of breast and neuroblastoma cell lines, respectively, suggesting that the Daam-family proteins may also contribute to invasion and metastasis in other malignancies." (PMID 29053101, 2017). "DAAM1 expression was undetectable in both neuroblastoma cell lines indicating that it is potentially not expressed in these cells." (PMID 24223803, 2013).
prostate carcinoma (2 papers, 2013 to 2020). A carcinoma that arises from epithelial cells of the prostate gland. "To validate ChIPs, we performed quantitative real-time PCR of the WNT gene, Disheveled-associated activator of morphogenesis 1 (DAAM1), co-expressed with ERG in prostate cancer." (PMID 23300998, 2013).
acute leukemia (1 paper, 2013). A clonal (malignant) hematopoietic disorder with an acute onset, affecting the bone marrow and the peripheral blood. "DAAM1 was enriched in 6 ChIPs with an at least two-fold enrichment over IgG control indicating that DAAM1 is an additional putative ERG target in acute leukemia." (PMID 23300998, 2013).
Anophthalmia (1 paper, 2015). Absence of the globe or eyeball. "In histological studies, Daam1+/gt embryos of diabetic dams that developed anophthalmia presented a very rudimentary eye, with no structures recognizable as the optic nerve or optic cup." (PMID 25540130, 2015).
astrocytoma (1 paper, 2011). "In this study, we found that miR-335 targeted a potential tumor suppressor Daam1, which promoted several oncogenic features such as growth and invasion in astrocytoma cells." (PMID 21592405, 2011). "To determine whether Daam1 is a functional target of miR-335 in malignant astrocytoma cells, we investigated whether reduction of Daam1 expression could mimic the growth and invasion-promoting effects of miR-335." (PMID 21592405, 2011). "We found that miR-335 targeted a potential tumor suppressor Daam1 in astrocytoma cells, which promoted several malignant features such as growth and invasion, whereas miR-335 inhibition could potently induce growth arrest, apoptosis and invasion repression both in vitro and in vivo." (PMID 21592405, 2011). "Therefore, we propose that the downregulation of DAAM1 induced by miR-335 may play a predominant role in mediating the pro-invasion effect of miR-335 in astrocytoma cells." (PMID 21592405, 2011).
bladder cancers (1 paper, 2019). "Furthermore, abnormal expression of PLK4, AURKB and DAAM1 is associated with poor outcomes in breast and bladder cancers." (PMID 31142743, 2019). "Furthermore, reduced expression of DAAM1 and elevated expression of DAAM2 were associated with high-grade bladder cancer." (PMID 31142743, 2019).
breast tumor (1 paper, 2019). "B. In breast tumor cell lines, collagen IV activates Dishevelled-associated activator of morphogenesis 1 (DAAM1) and RHOA to promote haptotaxis." (PMID 31052560, 2019).
COVID-19 (1 paper, 2024). A disease caused by infection with severe acute respiratory syndrome coronavirus 2. "Four DEPs (RAC1, CAMK2G, DAAM1, and RAC2) were enriched in the noncanonical Wnt pathway and two DEPs (TLE3 and CACYBP) were enriched in the canonical pathway in the COVID-19 comparison group." (PMID 39301288, 2024).
dyslexia (1 paper, 2024). A learning disorder characterized by an impairment in processing written words. "Among genetic variants that contributed especially to this impact mode, a dyslexia-disposing variant at the DAAM1 locus was associated with increased volume of the primary visual cortex (rs36065072, mode weight z score = 6.2)." (PMID 39693421, 2024).
gastric cancer (1 paper, 2022). A primary or metastatic malignant neoplasm involving the stomach. "For example, DAAM1 is overexpressed in gastric cancer and promotes tumor progression by regulating the ERK and AKT signaling pathways." (PMID 35281277, 2022).
Gonococcal infection (1 paper, 2021). "Gonococcal infection did not alter the mRNA abundance of the formins family members with the exception of FMNL3 and DAAM1." (PMID 34962968, 2021).
hyperglycaemia (1 paper, 2015). "Interestingly, our genetic analysis identified a similar eye phenotype to that produced by the Daam1 mutation, a malformation that worsens dramatically in the presence of environmental hyperglycaemia, both in vivo and in vitro." (PMID 25540130, 2015). "Interestingly, mice with a mutation in the Wnt-PCP component dishevelled-associated activator of morphogenesis 1 (Daam1, which is essential for cytoskeletal reorganization) display eye malformations similar to those resulting from maternal hyperglycaemia." (PMID 25540130, 2015). "Furthermore, eye defects in Daam1 mutant embryos are dramatically worsened by environmental hyperglycaemia, both in in vivo and in vitro settings." (PMID 25540130, 2015). "Hyperglycaemia affects the activity of important signalling pathways that are crucial for mouse embryogenesis, including the hypoxia (Hif1α), PDGFRa, Wnt-β-catenin (GSK3β, β-catenin) and the Wnt-planar cell polarity (PCP) (Vangl2, Daam1, Wnt5a, etc.)pathways." (PMID 25540130, 2015).
keloid (1 paper, 2022). An irregularly shaped, elevated mark on the skin caused by deposits of excessive amounts of collagen during wound healing. "In this present study, innovatively combining SVM-RFE and LASSO-logistic regression methods, we identified four biomarkers (STC2, SDC4, DAAM1, and NOX4) for keloid and further explored the role of ICI on keloid." (PMID 35719372, 2022).
leukemia (1 paper, 2013). A malignant (clonal) hematologic disorder, involving hematopoietic stem cells and characterized by the presence of primitive or atypical myeloid or lymphoid cells in the bone marrow and the blood. "Furthermore, we uncovered DAAM1, a WNT signaling and potent morphogenesis gene, and NUMB as novel putative targets of ERG in leukemia." (PMID 23300998, 2013).
Leydig cell tumor (1 paper, 2021). A sex cord-stromal tumor occurring in the testis and rarely in the ovary. "Herein, for the first time, the potential relationships between the cytoskeleton-associated proteins DAAM1 and PREP with different testicular disorders, such as classic seminoma (CS), Leydig cell tumor (LCT), and Sertoli cell-only syndrome (SOS), were evaluated." (PMID 34360857, 2021).